KRAS (KRas proto-oncogene, GTPase)
Diseases named in the same sentence as KRAS in open-access papers (continued):
Sharing a sentence is not in itself a finding about the gene and the disease.
colorectal cancer (continued). "Previous studies reported that BRAF, KRAS, and NRAS mutations occur in 10%–15%, 35–40%, and 2–7% of colorectal cancers, respectively." (PMID 26090613, 2015). "We investigated the impact of KRAS on CIP2A expression in colorectal cancer patients after colorectal liver metastasectomy." (PMID 25896895, 2015). "Detection of acquired resistance mutations through ctDNA analysis has been previously demonstrated in colorectal cancer with the evolution of mutant KRAS to EGFR blockade." (PMID 26524482, 2015). "As with lung cancer, the most well-described driver alterations in colorectal cancer (for example, ‘hotspot alterations’ in KRAS, BRAF, NRAS and PIK3CA) are concordant between primary tumors and metastatic lesions." (PMID 25808843, 2015). "In the present study, we were able to detect KRAS, BRAF, CD133 and PLS3 mutations in cell suspension enriched for all CTCs populations and in the corresponding primary tumor of 52 patients with colorectal cancer." (PMID 25902072, 2015). "The additional mutations in minor KRAS, NRAS, and BRAF were detected in 20% of the colorectal cancer patients in the PEAK study." (PMID 25954997, 2015). "KRAS mutations have been linked to the reduced efficacy of erlotinib in the treatment of NSCLC and to that of cetuximab in the treatment of colorectal cancer." (PMID 25962919, 2015). "Recently, mutations in KRAS have been detected in circulating tumor DNA in colorectal cancer patients with KRAS-wildtype (wt) cancers who had progressed on anti-EGFR therapy." (PMID 26474549, 2015). "We find that in a panel of isogenic SW48 colorectal cancer cells, endogenous Ras proteins are highly abundant with ≥260,000 total Ras protein copies per cell and the rank order of isoform abundance is KRAS>NRAS≥HRAS." (PMID 26560143, 2015). "Of the 13 patients for whom KRAS sequencing was performed, 4 patients (30.8%) had wild-type KRAS, which is associated with response to anti-EGFR therapy in colorectal cancer." (PMID 26161408, 2015). "Frequency and percentage of KRAS and BRAF mutations in normal (N), low-grade dysplasia (LGD), high-grade dysplasia (HGD) and colorectal cancer (CRC) samples." (PMID 26291085, 2015). "For instance, the KRAS gene mutated exclusively with the PTEN, VHL, RB1, and EGFR genes in large intestine cancers with high statistical significance." (PMID 26212640, 2015). "We used two colorectal cancer cell lines: SW48, which is KRAS wild-type, and HCT116, which carries a KRAS mutation." (PMID 25812794, 2015). "In colorectal cancer, the mitogen-activated protein kinase (MAPK) pathway is a commonly mutated pathway with 35–40% of patients having an activating mutation in KRAS and 5–10% of patients having an activating mutation in BRAF." (PMID 25688264, 2015). "Somatic mutations in KRAS, NRAS, and BRAF genes are related to resistance to anti-EGFR antibodies in colorectal cancer." (PMID 25954997, 2015). "Of interest, 2 of these 4 patients (colorectal cancer and NSCLC) also had KRAS G12 mutations in FFPE tumor samples and cfDNA." (PMID 25980577, 2015). "The results strongly suggest that targeting KRAS expression with cell-permeable G-quadruplex ligands is a promising approach to eventually identifying a compound effective in colorectal cancer therapy." (PMID 25853628, 2015). "We have previously shown that exosomes from mutant KRAS colorectal cancer (CRC) cells can be transferred to wild-type cells to induce cell growth and migration." (PMID 26132860, 2015). "We have established a NGS mutation assay for the detection of KRAS, NRAS, and BRAF mutations in clinical FFPE samples of colorectal cancer and have demonstrated a high preclinical and clinical performance." (PMID 25954997, 2015).
colorectal cancer (continued). "In this study, our primary aim was to assess the changes in the DNA methylation profile and also to examine KRAS and BRAF mutations in the progression of normal epithelium to colorectal cancer." (PMID 26291085, 2015). "In conclusion, our study suggests that specific epidemiologic and clinicopathologic characteristics were associated with KRAS and BRAFV600E mutations in a large cohort of Chinese colorectal carcinoma population." (PMID 25929517, 2015). "In colorectal carcinomas, 1 case presented concomitant KRAS and NRAS mutations and 2 cases had concomitant G12D and G13D KRAS mutations." (PMID 26435479, 2015). "Recently, MMR status, KRAS and BRAF mutation status have attracted remarkable attention due to their potential prognostic and predictive role in colorectal carcinomas." (PMID 25929517, 2015). "Mutations in genes such as KRAS, NRAS, BRAF and PIK3CA have become an important part of colorectal carcinoma evaluation." (PMID 26691448, 2015). "Currently, tumor KRAS gene status remains one of the most important predictive biomarker used in management of colorectal carcinoma." (PMID 25888291, 2015). "Mutations in the KRAS and BRAF genes are frequently found to be mutually exclusive in colorectal cancer." (PMID 25267307, 2014). "A PubMed search was conducted to identify all studies reporting on KRAS let-7 microRNA-binding site polymorphism (LCS6; rs61764370) and colorectal cancer outcome." (PMID 24890702, 2014). "KRAS codon 12 and 13 mutations have been inversely associated with BRAF mutation in colorectal cancer." (PMID 24885062, 2014). "Most of the data in colorectal cancer has been in KRAS mutant models since this population is in need of new novel therapies." (PMID 25401499, 2014). "In this study, we described a role for RasGAP as an important mediator of Rho signaling and tumorigenicity in a colorectal cancer cell line, and identified mutant KRAS as a key contributor to this pathway." (PMID 24465899, 2014). "In this study, we performed miRNA mimic screens in isogenic KRAS-Wild-type (WT) and KRAS-Mutant colorectal cancer (CRC) cell lines to identify miRNAs selectively targeting KRAS-Mutant cells." (PMID 25245095, 2014). "KRAS is mutated in ∼40% of colorectal cancer (CRC), and there are limited effective treatments for advanced KRAS mutant CRC." (PMID 24465899, 2014). "The HKe3 cells are derived from HCT116 colorectal cancer cell lines, but KRAS has been disrupted by genetic recombination (HKe3;)." (PMID 24875049, 2014). "A first-line therapy for patients with advanced colorectal cancer is the anti-EGFR (epidermal growth factor receptor) drug cetuximab; however, this is was thought to be ineffective for patients with KRAS mutations." (PMID 25109951, 2014). "Our current findings suggest that additional large-scale studies are warranted to assess clinical utility of KRAS codon 61 and 146 testing in colorectal cancer." (PMID 24885062, 2014). "Mutations in KRAS, BRAF and PIK3CA are the most common somatic alterations found in the colorectal cancer (CRC) patients from Western countries; but their prevalence and prognostic value have not been adequately assessed in Asian patients." (PMID 25367198, 2014). "In most of these studies, KRAS genotyping was performed on primary colorectal cancers, whereas anti-EGFR antibodies were used to treat the metastatic disease." (PMID 24884535, 2014). "Approximately 70% of KRAS-positive colorectal cancers (CRCs) have a CpG island methylator phenotype (CIMP) characterized by aberrant DNA hypermethylation and transcriptional silencing of many genes." (PMID 24623306, 2014). "This phase II study aims to evaluate the efficacy and safety of biweekly cetuximab in combination with oxaliplatin, leucovorin, and fluorouracil (FOLFOX-4) as first-line treatment of metastatic wild-type KRAS colorectal cancer." (PMID 25417182, 2014). "KRAS mutations in codons 12 and 13 are established predictive biomarkers for anti-EGFR therapy in colorectal cancer." (PMID 24885062, 2014).
colorectal cancer (continued). "As 45% of human colorectal cancers (CRC) harbor KRAS mutations, we sought to investigate its efficacy in KRAS mutant CRC cells, and examine its impact in combination with the topoisimerase-1 inhibitor, irinotecan." (PMID 24798549, 2014). "In conclusion, this study has provided new insights into the complexity of RasGAP and KRAS signaling, and reveals a novel role for RasGAP as an effector of KRAS and Rho pathway activity in colorectal cancer." (PMID 24465899, 2014). "The coexistence of PI3K and KRAS mutations and the mutual exclusion of KRAS and BRAF mutations had been previously reported in a subset of patients with colorectal cancer." (PMID 25313136, 2014). "Oncogenic activation of signaling pathways downstream of the EGFR, as induced by mutated KRAS or BRAF, is important for the progression of colorectal cancer." (PMID 25267307, 2014). "The survival rate of colorectal cancer (CRC) patients carrying wild-type KRAS is significantly increased by combining anti-EGFR monoclonal antibody (mAb) with standard chemotherapy." (PMID 25260023, 2014). "In spite of the clear role that KRAS alterations play in the pathogenesis and progression of colorectal cancer, several aspects concerning their clinical validation remain inconclusive or are not yet fully explored." (PMID 25491325, 2014). "However, the PGM also revealed a KRAS G13D mutation, presenting an noteworthy situation, as a randomized clinical trial previously demonstrated that tumors with a KRAS G13D mutation may also be sensitive to cetuximab in colorectal cancer patients." (PMID 24932229, 2014). "In colorectal cancer specimen KRAS amplifications were observed in only 0.67% (7/1039) or 2.1% (2/96) of tumors." (PMID 24676216, 2014). "Mutation profiles were 100% concordant for KRAS, NRAS, and BRAF, and were highly concordant for recurrent alterations in colorectal cancer." (PMID 25164765, 2014). "Recently, a broader mutation testing of RAS gene (at exons 2, 3, or 4 of both KRAS and NRAS) has been validated for treatment personalization in advanced colorectal cancer through the support of several studies." (PMID 24691006, 2014). "We focused on miR-126, a miRNA down-regulated in colorectal cancer and found that its expression was significantly lower in KRAS-Mutant tumors as compared to tumors expressing WT KRAS." (PMID 25245095, 2014). "Although EGFR-targeted therapy has been beneficial to colorectal cancer patients, several studies have showed this clinical benefit was restricted to patients with wild-type KRAS exon 2 colorectal cancer." (PMID 25427200, 2014). "PIK3CA mutations occur in approximately 15% of colorectal cancers and of these 8–9% have mutations in both PIK3CA and KRAS." (PMID 25401499, 2014). "miR-143 expression was decreased in human lung and colorectal cancers and was reported to inhibit KRAS translation in colorectal cancer cell." (PMID 25548562, 2014). "For example, colorectal carcinomas that are wild type for KRAS are frequently treated with monoclonal antibodies targeting the Epidermal Growth Factor Receptor (EGFR)." (PMID 24676216, 2014). "Accordingly, HDC9 KRAS/BRAF wild-type colorectal carcinoma cells - that weakly express Abi1 - display high levels of E-cadherin and no cleavage of Laminin5 indicated by a single y2′ band migrating at 100–105 kD." (PMID 24913355, 2014). "Funding of pharmacogenomic tests has been helped by investigators in Japan estimating that KRAS testing in selected patients with colorectal cancer before initiating cetuximab saved an estimated US$50 million per year compared to no testing." (PMID 23941275, 2013).
colorectal cancer (continued). "Mutations in the KRAS gene lead to KRas protein activation in many human tumors including NSCLC, pancreatic cancer and colorectal cancer." (PMID 23627488, 2013). "Conversely, of patients treated with panitumumab for KRAS wild-type colorectal cancer, 17% achieved partial remissions by RECIST criteria, 25% had tumor regression of >30% (estimated from measurement of waterfall plots) and 50% had tumor regression >10%." (PMID 23587187, 2013). "The cost of treatment for patients with colorectal cancer has also been reduced in France with the instigation of regional centers undertaking KRAS resting." (PMID 23941275, 2013). "In the present study, we examined the associations of specific KRAS and BRAF mutations with clinicopathological and tumour biological characteristics, and survival, in 525 incident cases of colorectal cancer from a prospective population-based cohort study." (PMID 24020794, 2013). "In this study, we have investigated the prognostic significance of KRAS codons 12 and 13, and BRAF mutations in incident colorectal cancer from a large prospective cohort study, with particular reference to sex-related differences." (PMID 24020794, 2013). "Our study confirms published data on the prognostic/predictive significance of BRAF, KRAS mutations and on the tumour expression of AREG, EREG mRNA in cetuximab-treated patients with colorectal cancer." (PMID 23374602, 2013). "In 2009, Luo and colleagues performed a genome wide screen to uncover synthetic dosage lethal interactors of an oncogenic KRAS mutant (KRASWT/G13D) in colorectal cancer cells." (PMID 24202319, 2013). "Activating KRAS and BRAF mutations predict unresponsiveness to EGFR-targeting therapies in colorectal cancer (CRC), but their prognostic value needs further validation." (PMID 24020794, 2013). "The vast majority of ITACs resembled colorectal cancer, showing deregulation of KRAS/BRAF genes that are involved in the early phases of colorectal cancer development." (PMID 23459231, 2013). "Our results showed almost perfect agreements in KRAS testing at a nationwide level despite different testing methods ensuring a cost-effective equal access to personalized colorectal cancer treatment." (PMID 23935912, 2013). "As a proof-of-concept we developed and validated a multiplexed in situ assay for the activating point mutations in KRAS codon 12 and 13 that are associated with resistance to anti-EGFR therapy in colorectal cancer." (PMID 24280411, 2013). "More than half of patients with KRAS-wild type advanced colorectal cancer (CRC) fail anti-EGFR monoclonal antibodies." (PMID 23374602, 2013). "In summary, the present study describes a novel small molecule inhibitor which can be used to effectively inhibit the Rho GTPase Cdc42 in the treatment of KRAS mutant colorectal cancers." (PMID 24279335, 2013). "In colorectal cancer, wild-type KRAS predicts sensitivity to anti-EGFR antibody therapies such as panitumumab." (PMID 23664091, 2013). "Here we report a case of a 75-year-old man with liver metastasis at 3 years after a successful transverse colectomy to treat KRAS wild-type colorectal cancer." (PMID 24304820, 2013). "Molecular classification of colorectal cancer (CRC) is currently based on microsatellite instability (MSI), KRAS or BRAF mutation and, occasionally, chromosomal instability (CIN)." (PMID 23165447, 2013).
colorectal cancer (continued). "In summary, PIK3CA-mutated colorectal carcinomas are more likely to develop in the proximal colon, to demonstrate high levels of CIMP, KRAS mutation and loss of MGMT expression." (PMID 23785428, 2013). "For KRAS analysis, this was concordant across all technologies, however the BRAF mutation at codon 600 was called in 1/3 colorectal carcinoma samples though at a low coverage equal to 4.38% and only by 1/4 analysis (IonTorrent)." (PMID 23922754, 2013). "KRAS and PIK3CA mutations frequently coexist in patients with colorectal cancer, and are associated with clinical characteristics and outcome." (PMID 22675430, 2012). "Mutation of BRAF and KRAS can result in aberrant c-Myc and SIRT1 protein deacetylase expression in the colorectal cancer." (PMID 23455493, 2012). "Currently, KRAS is the only potential biomarker for predicting the efficacy of anti-EGFR monoclonal antibodies (mAb) in colorectal cancer (CRC)." (PMID 22043994, 2012). "We previously reported that simultaneous down-regulation of both β-catenin and KRAS was necessary to induce significant cell death and tumor growth inhibition of colorectal cancer cells." (PMID 23227266, 2012). "Conversely, treating cells with a miR-143 mimic or overexpressing miR-143 in colorectal cancer cells, knocked down expression of KRAS, decreased activation of ERK1/2, and blocked cell proliferation." (PMID 23202889, 2012). "We recently demonstrated that HKe3 cell line, which is a human colorectal cancer (CRC) HCT116 cell line disrupted at oncogenic KRAS, in 3-D Matrigel culture (3 DC) manifests an organized structure resembling a colonic crypt." (PMID 22830422, 2012). "The levels of KRAS mRNA have also been found to vary randomly in colorectal cancer despite consistent up-regulation of KRAS protein expression." (PMID 22384141, 2012). "Similar to KRAS mutations, EGFR overexpression has also been linked to poor prognosis and increased risk of metastasis in colorectal cancer and, therefore, represents a promising therapeutic target." (PMID 23202889, 2012). "Role of KRAS, BRAF and PIK3CA mutations in pathogenesis of colorectal cancer (CRC) has been recently investigated worldwide." (PMID 22931052, 2012). "Mutations of KRAS and BRAF genes are frequently found to be mutually exclusive in colorectal cancer, both in Western and Chinese patients." (PMID 22586484, 2012). "To date, KRAS status is the only predictive biomarker that defines the utility of treatment choice in colorectal cancer: mutant KRAS patients are excluded from cetuximab treatment." (PMID 22701615, 2012). "In this paper we highlight the current state of understanding of KRAS, with a specific emphasis on the role of KRAS in colorectal cancer." (PMID 23202889, 2012). "For example, it has been described that KRAS induces the activity of the small GTPase Rac, thus modulating colorectal cancer cell adhesion and motility." (PMID 22808230, 2012). "In conclusion, we show that KRAS and PIK3CA mutations are frequently associated in patients with colorectal cancer." (PMID 22675430, 2012). "By better understanding interactions between KRAS and other genes, we may then take advantage of these synthetic lethal combinations to provide additional options to treat chemotherapy-or cetuximab-refractory colorectal cancer patients harboring KRAS mutations." (PMID 23202889, 2012). "Models VARI-LTM-044 colorectal cancer and VARI-LTM-034 pancreatic cancer both had a single KRAS mutation; melanoma models VARI-LTM-086 and VARI-LTM-027 had BRAF and NRAS mutations, respectively." (PMID 22709571, 2012). "In summary, we observed a moderate rate of KRAS mutations (145/478; 30.3%) or PIK3CA mutations (67/384; 17.4%) and a very low rate of BRAF mutations (1/384; 0.3%) in a cohort of primary colorectal carcinomas." (PMID 22931052, 2012).